ZNF682 (zinc finger protein 682)
Description:
May be involved in transcriptional regulation.
Synonyms: BC39498_3
Tractability: PROTAC: ubiquitination databases record sites on it.
Gene: Protein-coding gene on chromosome 19 (19,997,058 to 20,039,505, reverse strand). Ensembl gene ENSG00000197124.
Subcellular location: Nucleus
Subcellular location (Human Protein Atlas): Golgi apparatus
Pathways (Reactome):
Gene expression (Transcription): Generic Transcription Pathway
Gene Ontology:
Molecular function: DNA-binding transcription factor activity, RNA polymerase II-specific; RNA polymerase II cis-regulatory region sequence-specific DNA binding
Biological process: regulation of DNA-templated transcription; negative regulation of transcription by RNA polymerase II
Cellular component: nucleus
Genetic constraint (gnomAD): Loss-of-function variants: 32 observed, 39.15 expected, observed/expected ratio (o/e) 0.82, 90% interval 0.62 to 1.1. The upper end of that interval is the gene's LOEUF score, 1.1, which puts it in group 4 of 6, group 1 being the genes least tolerant of losing a copy. Missense variants: 561 observed, 606.65 expected, observed/expected ratio (o/e) 0.92, 90% interval 0.86 to 0.99. Synonymous variants: 178 observed, 203.63 expected, observed/expected ratio (o/e) 0.87, 90% interval 0.77 to 0.99.
Homologues: Orthologues: chimpanzee ZNF682 (99% identical), macaque ZNF682 (95% identical), mouse Zfp738 (51% identical), mouse Zfp457 (49% identical), mouse Zfp595 (49% identical), rat AABR07009105.1 (46% identical), mouse Zfp953 (32% identical). Paralogues in human: ZNF708 (64% identical), ZNF681 (64% identical), ZNF429 (63% identical), ZNF85 (63% identical), ZNF254 (63% identical), ZNF726 (63% identical), ZNF493 (63% identical), ZNF724 (62% identical), ZNF728 (62% identical), ZNF695 (61% identical), ZNF43 (60% identical), ZNF93 (60% identical), and 164 more.
Diseases named in the same sentence as ZNF682 in open-access papers:
ZNF682 is named in the same sentence as 4 diseases in open-access papers, as found by Europe PMC text mining. Sharing a sentence is not in itself a finding about the gene and the disease. The quoted sentences say what the papers report.
breast adenocarcinoma (1 paper, 2014). "Among these, ZNF257 and ZNF682 were previously reported to be upregulated in lung and bone metastases, relative to the primary breast adenocarcinoma, and were speculated to be putative metastasis genes." (PMID 24405831, 2014).
carcinoma (1 paper, 2021). A malignant tumor arising from epithelial cells. "The remaining signature genes, CPXM2, ENPP5, SAMD13, SLC52A1, ZNF682, ZNF835, ZNF571-AS1 and U91328.1, have not been related to carcinoma, yet." (PMID 33672117, 2021).
ZNF682 also shares sentences with these, for which no sentence is quoted: dysplasia (1 paper); lung carcinoma (1).